DCLK1 (doublecortin like kinase 1)
Diseases named in the same sentence as DCLK1 in open-access papers (continued):
Sharing a sentence is not in itself a finding about the gene and the disease.
cancer (continued). "DCLK1 interacts with multiple cancer pathway molecules, suggesting its function in carcinogenesis, metastasis, and diagnosis." (PMID 36250024, 2022). "Our findings revealed an important role of DCLK1, a marker of some cancer stem cells, in mediating thrombin-stimulated IL-8/CXCL8 expression in human lung epithelial cells." (PMID 36369000, 2022). "In summary, our research uncovered that DCLK1 was correlated with 5‐fluorouracil resistance, and functionally promoted cancer stemness and 5‐fluorouracil resistance in CRC." (PMID 35522902, 2022). "Mechanistically, we elucidated that DCLK1 promoted 5‐fluorouracil resistance in CRC by CCAR1/β‐catenin pathway‐mediated cancer stemness." (PMID 35522902, 2022). "Then we investigated the effect of inhibition of DCLK1‐mediated cancer stemness by blocking β‐catenin on DCLK1‐mediated 5‐fluorouracil resistance." (PMID 35522902, 2022). "The up-to-date literature has suggested that DCLK1 is a key player for cancer progression and metastasis in various cancers." (PMID 36250024, 2022). "Collectively, these data suggested that targeting DCLK1 suppressed 5‐fluorouracil resistant CRC cells through inhibiting CCAR1/β‐catenin pathway‐mediated cancer stemness." (PMID 35522902, 2022). "Ever since DCLK1 was first observed outside the CNS, it has been used as a marker for various cancers." (PMID 36250024, 2022). "Doublecortin-like kinase 1 (DCLK1) has been recognized as a marker of cancer stem cell in several malignancies." (PMID 36369000, 2022). "Collectively, we demonstrated that DCLK1 was closely correlated with 5‐fluorouracil resistance, and functionally promoted cancer stemness and 5‐fluorouracil resistance in CRC." (PMID 35522902, 2022). "After the preliminary description of DCLK1 in the CNS, current advances have almost completely targeted on regions outside the CNS, showing the location of DCLK1 tuft cells throughout the digestive system and several cancer types." (PMID 36250024, 2022). "Experimentally, our in vitro and in vivo findings confirmed that DCLK1 kinase activity promotes cancer cell survival, aggressiveness and stemness which were previously mainly determined through the genetic manipulation of DCLK1 expression 19, 45-51." (PMID 35910805, 2022). "DCLK1, a member of the protein kinase superfamily and the double cortin family, is highly expressed in several types of cancers and has recently been identified as a tumor stem cell marker in CRC." (PMID 36210463, 2022). "To date, some reviews were conducted regarding DCLK1 importance in cancer progression; however, data of the available literature do not provide a complete and systematic overview." (PMID 35717205, 2022). "Considering that CSCs were critical for cancer initiation, progression, metastasis, relapse and therapy resistance, we found that DCLK1, a CSCs marker, weakened the sensitivity of CRC cells to 5‐fluorouracil." (PMID 35522902, 2022). "TGFβ2 was significantly negatively correlated with mRNAsi and significantly positively correlated with cancer stem cell markers DCLK1, Lgr5, CD133 and CD44." (PMID 35620459, 2022). "Today, several studies on DCLK1 as potent tumor inducers in various cancers have been confirmed DCLK1 to have critical role in regulating cancer pathways." (PMID 36250024, 2022). "Together, these findings demonstrate that DCLK1-IN-1 downregulates pluripotency factor expression and powerfully inhibits cancer cell stemness." (PMID 34830884, 2021). "Given the close link between DCLK1 and cancer, research on DCLK1 small molecule inhibitors has been progressing in recent years." (PMID 33762936, 2021). "EMT is the key process driving cancer metastasis and DCLK1 is a regulator of EMT-related transcription factors." (PMID 33762936, 2021). "Lgr5-positive gastric cells expand during gastric tissue repair and metaplasia, and a subset of small intestinal Lgr5-positive cells co-expressing Dclk1 are described to behave as cancer stem cells." (PMID 33627749, 2021).
cancer (continued). "Cumulative evidence has verified that DCLK1 expression can support CSCs self-renewal, cancer growth, EMT, and metastasis in both early and advanced cancer stages." (PMID 34268251, 2021). "DCLK1 deregulation has been reported in various cancers, including gastric, pancreatic, breast, colorectal, and kidney." (PMID 34545159, 2021). "Doublecortin-like kinase 1 (DCLK1) is a cancer stem cell marker that is highly expressed in various types of human cancer, and a protein kinase target for cancer therapy that is attracting increasing interest." (PMID 33762936, 2021). "In particular, the discovery of DCLK1-IN-1, a new selective chemical probe for the DCLK1 kinase, has enabled us to comprehensively investigate the precise roles of DCLK1 in cancer." (PMID 33762936, 2021). "DCLK1 is a cancer stem cell (CSC) marker, which promotes initiation, aggressiveness, and metastasis through many pathways, such as the Wnt/β-catenin pathway." (PMID 34069906, 2021). "XMD-17-51 was found to elicit an anti-cancer activity, partly through the inhibition of DCLK1, and be a potential candidate for cancer therapy." (PMID 33762936, 2021). "Especially, recent studies have identified DCLK1 as a cancer stem cell (CSC) marker of malignant cells in the small intestine and pancreas." (PMID 34445192, 2021). "As a consequence, many studies have focused on developing small-molecule inhibitors against DCLK1 kinase activity in an effort to control cancer growth." (PMID 34310279, 2021). "Recently, DCLK1-IN-1 was tested against the DCLK1-S isoforms present in certain cancer cells lines and patient derived organoid model of pancreateic cancer." (PMID 34545159, 2021). "Based on the relevancy of DCLK1 to the progression of a variety of cancer types, understanding DCLK1 autoregulation is critical in determining its biological function in healthy versus disease states." (PMID 34310279, 2021). "Doublecortin-like kinase 1 (DCLK1) is an intestinal and pancreatic stem cell marker that showed overexpression in a variety of cancers." (PMID 34268251, 2021). "In this study, we demonstrate that DCLK1 down-regulation in HNSCC cells by siRNA-mediated knockdown or through pharmacologic inhibition in vitro resulted in reduced cancer cell proliferation, migration, and cell invasion." (PMID 34336664, 2021). "Overexpression of DCLK1 has been reported in multiple cancers, including colon, pancreatic, renal cell carcinoma and rectal neuroendocrine tumours." (PMID 34545159, 2021). "The microtubule-associated protein, doublecortin-like kinase 1 (DCLK1), is highly expressed in a range of cancers and is a prominent therapeutic target for kinase inhibitors." (PMID 34310279, 2021). "Together, these findings suggest that DCLK1 is a promising target to enhance antitumor effect through regulating TIME in some types of cancer." (PMID 33348546, 2020). "We showed the interaction of MACC1 with the cancer stem cell (CSC) marker DCLK1, which contributes to metastasis formation in different tumor entities." (PMID 32756469, 2020). "Others such as doublecortin-like kinase 1 (DCLK1)—a proposed cancer stem cell marker—show preclinical potential." (PMID 32664619, 2020). "In this regard, it has been recently reported that Dclk1 discriminates between cancer and normal stem cells in the intestine." (PMID 32296643, 2020). "Although DCLK1 is upregulated in angiogenesis and regulates chemotherapy resistance and cancer stemness by WNT signaling, knowledge of the effect of DCLK1 on hypoxia-driven immune cells, endothelial cells, blood vessels, and ECM remains limited." (PMID 33348546, 2020). "DCLK1 has been regarded as a new potential cancer stem cell (CSC) marker in several types of cancer." (PMID 32423385, 2020). "This highlights the relevance of DCLK1 as a major target in two different cancer entities (colon and pancreas), targeted by two different compounds of saffron (crocin and crocetin)." (PMID 32756469, 2020).
cancer (continued). "More recently, DCLK1′s role in regulating the inflammatory, pre-cancer, and tumor microenvironment including its ability to modulate immune cell mechanisms has started to come into focus." (PMID 33348546, 2020). "The mRNA and protein levels of the cancer stem cell markers DCLK1 and ALDH1A1 remained unchanged in both shHPGD- and shGLI1-knockdown HT-29 and Caco-2 cell-derived colonospheres, even after LTC4 stimulation, compared with their unstimulated counterparts." (PMID 32814764, 2020). "Doublecortin-like kinase 1 (DCLK1) is a tumor stem cell marker in colon, pancreatic, and potentially other cancers that has received wide attention recently." (PMID 33348546, 2020). "In the gastrointestine, Dclk1+ tuft cells are thought to be facultative progenitors that act as an origin of cancers in a specific condition." (PMID 33542169, 2020). "In summary, DCLK1-expressing TCs play an important role in stimulating gastrointestinal epithelial stem cells in the microenvironment and contributing to cancer progression." (PMID 33348546, 2020). "There is growing evidence indicating that DCLK1 is essential for maintaining cancer stemness and promotion of cancer initiation and metastasis." (PMID 31223610, 2019). "DCLK1 is a member of the protein kinase super family and the doublecortin family, which is overexpressed in many cancers, including colon, pancreas, liver, esophageal, and kidney cancers." (PMID 31684193, 2019). "Further evaluation of the effect of treatment in BE and EAC on stem cell markers, such as DCLK1, will enhance understanding regarding recurrence or progression to cancer in these patients and stimulate continued improvement in treatment and survival." (PMID 30899515, 2019). "Further in our previous studies, we have shown that DCLK1 acts as stem cell marker in cancer cells as well as a quiescent marker in normal cells of the intestine." (PMID 31608135, 2019). "Doublecortin like kinase-1 (DCLK1) is a cancer stem cell marker with elevated expression in BE patients with high grade dysplasia and/or EAC." (PMID 30899515, 2019). "To measure DCLK1 mRNA expression and determine if the levels correlated with patient survival, we analyzed the Illumina HiSeqV2 RNA-sequencing The Cancer Genome Atlas (TCGA) database." (PMID 31878090, 2019). "Analysis of DCLK1 expression across tissue types demonstrates a favorable pattern for targeted cancer therapy." (PMID 31467540, 2019). "We found that DCLK1 promoted cell migratory and invasive abilities, which are typical characteristics of cancer metastasis." (PMID 31223610, 2019). "Dclk1 is expressed in a variety of cancer cells, with a functional role in tumor growth and progression." (PMID 30208879, 2018). "miR-15a inhibits several important genes (BCL2, BMI1, YAP1 and DCLK1), decreasing cancer progression and resistance." (PMID 29416778, 2018). "Taken together, these studies have suggested that DCLK1 is a downstream molecule of the Wnt signaling pathway and is associated with direct LEF binding and cancer initiation." (PMID 28757546, 2017). "We focused on DCLK1 because it is a newly identified CSC marker which is functionally involved in driving cancer carcinogenesis and cancer progression." (PMID 28244691, 2017). "Prior work suggests that Dclk1 marks stem cells, being able to differentiate cancer from normal stem cells." (PMID 28626429, 2017). "Doublecortin-like kinase 1 (DCLK1) has been found to be involved in malignant biological behavior of cancers and poor prognosis of cancer patients." (PMID 29246000, 2017). "When sensitivity and specificity were considered simultaneously, the AUC of DCLK1 was 0.78, suggesting that the test performance of DCLK1 in discerning cancer tissues is reasonably good." (PMID 29246000, 2017). "The overall combined sensitivity and specificity for DCLK1 in distinguishing malignant tumors were 0.58 and 0.90, respectively." (PMID 29246000, 2017).
cancer (continued). "The aim of this meta-analysis was to systematically clarify the relationships between expression level of DCLK1 and clinicopathological characteristics in tumors and assess its clinical value in cancer diagnosis and prognosis." (PMID 29246000, 2017). "Despite these limitations, the meta-analysis still provided credible evidence that up-regulation of DCLK1 was an early event in the carcinogenesis and progression of malignant tumors." (PMID 29246000, 2017). "In order to investigate the association between DCLK1 expression and clinical outcome in malignant tumors, patients were divided into DCLK1-high and DCLK1-low groups." (PMID 29246000, 2017). "In addition, we found DCLK1 has higher diagnostic accuracy for malignant tumors in small samples using univariate meta-regression analysis and subgroup analysis, suggesting that sample size may be partially the cause of heterogeneity in sensitivity and specificity." (PMID 29246000, 2017). "Furthermore, we also found that patients with high DCLK1 expression had significantly poor overall survival, indicating that DCLK1 may be a promising biomarker that helps to identify patients with a high risk for recurrence in cancer." (PMID 29246000, 2017). "DCLK1 is therefore considered as an attractive and potential therapeutic target in the treatment of malignant tumors." (PMID 29246000, 2017). "The overall pooled sensitivity and specificity were 0.58 (95% CI = 0.51–0.66) and 0.90 (95% CI = 0.82–0.95), respectively, which suggested that DCLK1 had a relatively considerable accuracy in detecting malignant tumors." (PMID 29246000, 2017). "Eleven studies investigated the expression patterns of DCLK1 in various cancer and normal tissues, which included 742 cancer cases and 508 normal controls." (PMID 29246000, 2017). "Due to the limitations of currently available evidence on the therapeutic effects and molecular biology of DCLK1 in malignant tumors, Further studies are warranted to investigate these in more detail." (PMID 29246000, 2017). "Our collaborator reported that DCLK1+ cells are quiescent and are involved in cancer initiation upon injury." (PMID 27335684, 2016). "We crosschecked the data by detecting changes in Dclk1 protein, which is an exclusive marker for cancer stem cells of the intestine." (PMID 27388564, 2016). "Taken together, these findings support the notion that DCLK1 is critical for cancer initiation, growth, stemness, EMT, and metastasis, and that DCLK1+ cells can identify cancer stem-like cells that are critical for therapy resistance and cancer recurrence." (PMID 27335684, 2016). "DCLK1 is overexpressed in many cancers, including colon, pancreas, liver, kidney, and esophageal cancer." (PMID 27335684, 2016). "Researchers have strongly suggested targeting DCLK1 for effective cancer treatment and improved survival." (PMID 27335684, 2016). "The result was in contrast to its tumor promoting roles in gastrointestinal cancers, suggesting different functional roles of DCLK1 in different type of cancers." (PMID 26621833, 2016). "Studies from us and others supported that DCLK1 expression is critical for cancer growth, EMT, and metastasis." (PMID 27335684, 2016). "DCLK1 expression showed a differential expression in different molecular subtypes with the highest prevalence in luminal cancers (p < 0.001)." (PMID 26621833, 2016). "It appears that the association of DCLK1 with outcome in luminal cancers is mainly related to the relationship with IBC-NED, which are clustered within the luminal group of cancers." (PMID 26621833, 2016). "Functional links between EMT, stemness, and DCLK1 are correlated with cancer resistance, metastasis, and recurrence." (PMID 27335684, 2016). "Doublecortin-like kinase 1 (DCLK1), a cancer stem cell marker, is functionally involved in maintaining cancer stemness and the process of EMT important for cancer initiation, cancer metastasis, and secondary tumor formation." (PMID 27335684, 2016).
cancer (continued). "DCLK1 specifically marked cancer stem cells (CSC) that self-renew and generate tumor progeny in ApcMin/+ mice." (PMID 26621833, 2016). "DCLK1 is overexpressed in many cancers, including colon, pancreas, liver, esophageal, and kidney cancer." (PMID 27335684, 2016). "As we have seen in other cancers and cancer cell lines, knockdown of DCLK1 reduced the expression of stem cell pluripotency factors MYC, NANOG, POU5F1/OCT4, and SOX2 in Caki-2 cells." (PMID 25605241, 2015). "Our results further revealed plasticity of DCLK1-positive human hepatocytes and potential dedifferentiate into cancer-stem-like phenotypes." (PMID 25948779, 2015). "Our laboratory and others have shown overexpression of the markers DclK-1, CD-44 and CD-133, representing cancer stemness, in PC." (PMID 25906749, 2015). "Pancreata of mice receiving combination treatment showed significantly fewer Dclk1-positive cancer stem-like cells, inhibition of COX-2, 5-LOX, PCNA, EGFR and β-catenin expression (p < 0.05–0.0002), increased p21 expression." (PMID 26429877, 2015). "A recent report focusing on a particular region of the DCLK1 α-promoter demonstrated hypermethylation in cholangiocarcinoma suggesting gene knockdown and a potential tumor suppressor function for DCLK1 in that cancer." (PMID 25605241, 2015). "The specificity of LRRK2-IN-1 for DCLK1 and the results of our studies support the development of DCLK1 kinase inhibitors against cancer." (PMID 24885928, 2014). "Previous work from us and others supported that DCLK1 expression in cancer is critical for cancer growth, EMT, and metastasis." (PMID 25211188, 2014). "We investigated effects of fluvastatin (FLV) on microtubule-associated and cancer stem cell marker (CSC), doublecortin-like kinase 1 (DCLK1) during HCV-induced hepatocarcinogenesis." (PMID 24260365, 2013). "Because DCLK1 is frequently overexpressed in pre-neoplastic and cancer tissues, we investigated FLV effects on the GS5-DCLK1 cells, which overexpress human DCLK1 tagged with red florescence protein (RFP) at the N-terminus." (PMID 24260365, 2013). "Another potential cancer stem cell marker Lgr5 was also studied and found to be affected in similar manner to DCLK1." (PMID 23533514, 2013). "We have previously demonstrated that downregulation of DCLK1 can upregulate critical miRNAs in both in vitro and in vivo cancer models and results in downregulation of c-MYC, KRAS, NOTCH1 and EMT-related transcription factors." (PMID 24040120, 2013). "Therapeutic strategies targeting DCLK1, alongside radioprotective agents, immunomodulators, and senolytics, may enhance regeneration, limit fibrosis, and eradicate therapy-resistant cancer stem cells." (PMID 40563698, 2025). "The mechanism by which DCLK1 regulates Hippo signaling and cancer stemness was further investigated in vitro by methods such as Western blot analysis, quantitative real-time PCR analysis, immunofluorescence staining, and luciferase reporter assays and in vivo by animal studies." (PMID 39781521, 2025). "Growing evidence supports that DCLK1 is highly enmeshed with cancer cell physiology." (PMID 40869256, 2025). "Studies on other cancers have shown that DCLK1 activates KRAS, a type of G-protein." (PMID 40863727, 2025). "Importantly, they showed that DCLK1 inhibitor can block cancer stem cells mediated by the CCAR1/β-catenin signaling pathway and thus suppress 5-fluorouracil-resistant CRC cells in vitro and in vivo." (PMID 40978202, 2025). "DCLK1 is a marker for both tuft and cancer stem-like cells (CSCs)." (PMID 40563698, 2025). "These cytokines promoted the stemness of doublecortin-like kinase 1 (Dclk1)+ tufted cells, which may serve as a cellular source of cancer." (PMID 40508145, 2025). "Accumulating evidence identifies DCLK1 as a promising target for cancer therapy." (PMID 40775208, 2025). "Additionally, as a putative CSC marker, DCLK1 is known to maintain stem cell-like properties in cancers." (PMID 40775208, 2025).